IGF1R (insulin like growth factor 1 receptor)
Diseases named in the same sentence as IGF1R in open-access papers (continued):
Sharing a sentence is not in itself a finding about the gene and the disease.
breast cancer (continued). "Moreover, Ginsenoside Rp1 induced apoptosis in MCF-7, MDA-MB-231, and T-47D breast cancer cells through the insulin-like growth factor 1 receptor (IGF-1R)/Akt signaling pathway, thereby inhibiting breast the growth of breast cancer cells." (PMID 37818185, 2023). "Increased IGF1 receptor (IGF1R) expression is found in 50% of breast cancers." (PMID 38136416, 2023). "In our study, whilst we found that both IGF1R and IR were detectable in all breast cancer subtypes, no subtype was associated with higher levels of IGF1R or IR expression." (PMID 36920947, 2023). "Moreover, elevated insulin/IGF1R signaling confers drug resistance of breast cancer cells to antiestrogens." (PMID 37237509, 2023). "Studies have shown that women with high IR/IGF1R ratio have poor breast cancer prognosis." (PMID 37686596, 2023). "High IGF-1R expression or phosphorylation levels in tumor samples were found to correlate with lower response rates to trastuzumab-based bio-chemotherapy in HER-2+ breast cancer." (PMID 38406785, 2023). "IGF1R is a trans-membrane tyrosine kinase receptor and frequently up-regulated in breast cancer." (PMID 38034788, 2023). "Our results suggest that CR may diminish IGF1/IGF1R signaling in two ways: by reducing circulating ligand, and by repressing Igf1r expression in a miR-15b-dependent manner in vivo (mammary tumors)." (PMID 37686596, 2023). "The role of IGF-1 is mediated by IGF-1R, which is overexpressed in breast cancer." (PMID 36755926, 2023). "In recurrent breast cancer, IGF-1R has been shown to heterodimerize with HER-2." (PMID 38406785, 2023). "Since IGF-1R has been described as an anti-apoptotic factor in breast cancer cells, increased apoptosis observed in TFPI-stimulated MDA-MB-231 cells may be a consequence of diminished IGF-1R levels as a result of TF pathway inhibition." (PMID 36980251, 2023). "Women with higher IR/IGF1R ratio showed poor breast cancer prognosis as well as hyperinsulinemia." (PMID 35710446, 2022). "Nevertheless, results from these trials will inform the greater clinical community whether diet may be a viable therapeutic strategy, either alone or in conjunction with pre-existing IGF-1R-targeting therapies, for breast cancer patients." (PMID 36556357, 2022). "The IGF1R-IRS1/2 signaling axes may be important in breast cancers as at least 50% of breast tumors have activated IGF1R." (PMID 35846378, 2022). "In a nested case–control study of 312 women, cytoplasmic, but not membrane, IGF-1R staining in benign breast tissue was associated with higher risk of developing breast cancer." (PMID 36556357, 2022). "Preclinical studies using both in vitro and in vivo model systems and Phase I clinical trials have shown that treatment with anti-IGF-1R antibodies can inhibit several steps in breast cancer progression, including proliferation, survival, motility, invasion, and metastasis." (PMID 36556357, 2022). "However, the importance of IGF-1R-specific functions in breast cancer is supported by the fact that an IGF-1-driven gene signature is associated with poor disease outcomes." (PMID 36556357, 2022). "More recent observations suggest that nuclear IGF-1R may also play a significant role in breast cancer." (PMID 36556357, 2022). "Interestingly, a recent study proposed that IR/IGF1R ratio is an important factor for breast cancer prognosis." (PMID 35710446, 2022). "In contrast, this expression pattern has an unfavorable prognostic impact on DFS in TN breast tumors, suggesting that subcellular localization of IGF-1R may play different roles in different breast cancer subtypes." (PMID 36556357, 2022). "Impaired interactions between ERα and zinc-finger proteins may lead to aberrant IGF1R expression in breast cancer cells." (PMID 36479090, 2022). "Besides, we demonstrated that IGF1R-mediated oncogenic functions of GASP1 in breast cancer cells through a series of in vitro rescue experiments." (PMID 36042202, 2022).
breast cancer (continued). "Breast cancer cells can develop metformin resistance by triggering IGF-1R target insulin receptor substrate-1 (IRS-1)/ERK signaling through overactivation of FGFR1; IRS-1 acts as a critical crosstalk mediator between IGF-1R and FGFR1 pathways, encompassing a feedback loop between IRS-1 and MAPK/ERK." (PMID 36017326, 2022). "Diosgenin was anticipated to interact with IGF1R in the current investigation, potentially preventing breast cancer metastasis and tumor invasion, which could be PI3K-Akt driven, as previously discussed." (PMID 36686654, 2022). "In conclusion, current study may provide an important information in the regulatory mechanism of how breast cancer cells have acquired higher IR/IGF1R ratio." (PMID 35710446, 2022). "We tested whether in vitro m708.5 sensitivity could be correlated with IGF-1R in breast cancer cells." (PMID 35399718, 2022). "IGF-1R/IR Receptor Tyrosine Kinase Inhibitors (RTKi): Small molecule inhibitors that target receptor tyrosine kinase activity of the IGF-1R (RTKi) have also been developed for use in breast cancer." (PMID 36556357, 2022). "IGF1R signaling negatively impacts immune surveillance in breast cancer patients, as evidenced by IGF1R phosphorylation resulting in slight CD8+ CTL infiltration, significant infiltration of FOXP3+ regulatory T cells, immunosuppressive CD163+ macrophages, and poor prognosis." (PMID 35463082, 2022). "Furthermore, low levels of IGF1R predict worse overall patient survival across all breast cancer subtypes." (PMID 36568144, 2022). "Additionally, CSCs from human breast cancer xenografts exhibit increased IGF-1R phosphorylation, which indicates increased pathway activity." (PMID 36556357, 2022). "High expression of let-7, miRNAs-21, -23, and −27a has been linked with drug resistance in ovarian cancer, whereas miRNA-452 was shown to be significantly down-regulated in adriamycin-resistant breast cancer cells; targeting insulin-like growth factor-1 receptor (IGF-1R)." (PMID 35879960, 2022). "Two tumor pathologies were described where smaller tumors histologically presented as solid sheets of cells with sparse extracellular space, similar to CD8α-IGF1R tumors, and larger tumors were more vacuous and likened to the phenotype of Wnt-driven mammary tumors." (PMID 35784559, 2022). "Similarly, in luminal breast cancer, IGF1R is up-regulated and promoted antiestrogen resistance by activating PAK2/PIX." (PMID 36359853, 2022). "We published previously that low IGF1R expression predicts poor patient survival across all breast cancer subtypes suggesting negative functional consequences from loss of IGF1R expression." (PMID 36568144, 2022). "Additionally, the IGF-1 receptor (IGF-1R) signalling pathway has been shown to play important role in numerous human cancers, including breast cancer." (PMID 36432711, 2022). "In hormone-dependent breast cancer cells, the IGF-1R and ERα are frequently co-expressed." (PMID 33816477, 2021). "It has also been reported that hyperinsulinemia could activate the insulin receptor (IR)/insulin-like growth factor 1 receptor (IGF-1R) signaling pathway to promote the development of breast cancer." (PMID 34434893, 2021). "The mechanism by which vitamin D may prevent breast cancer and lead to improved cancer outcomes may be, in part, due to the downregulation of the IGF-1R pathway." (PMID 35008602, 2021). "Consequently, inhibition of IGF-1R leads to a reduced bone metastasis of breast cancer cells due to inhibition of the AKT signaling." (PMID 34064589, 2021). "Additionally, the IGF-1R inhibitor PQIP diminishes the breast cancer cell-induced osteolysis in a bone metastasis mouse model by inhibiting the IGF-1/IGF-1R/AKT axis-dependent osteoclast formation." (PMID 34064589, 2021). "To investigate whether a similar mechanism exists in HER2-positive breast cancer cells to control IGF-1R signaling, we treated SKBR3 and BT474 cells with a series of doses of rhIGF2." (PMID 33976188, 2021).
breast cancer (continued). "Moreover, up-regulation of IGF1R is used by breast cancer cells as a mechanism of resistance to HER2, EGFR and anti-estrogen inhibitors." (PMID 34441794, 2021). "Higher GHR, IGF-1, and IGF-1R expression are observed on breast cancer cells in humans." (PMID 34530525, 2021). "Targeting the IGF-1/IGF-1R/S100A7 pathway may therefore represent a further useful approach for blocking disease progression in breast cancer patients with dysregulated IGF-1 signaling." (PMID 33557316, 2021). "It is established that some of the disparity in breast cancer outcomes may be related to the more notable dysregulation of the IGF-1R pathway in African American patients." (PMID 35008602, 2021). "Thus, calycosin exerts an inhibitory effect on breast cancer growth by ERβ-mediated regulation of IGF-1R signaling pathways." (PMID 34462889, 2021). "In this study, we seek to investigate the contributions of IGF2 and the insulin receptor substrate-1 (IRS1) to Herceptin resistance and elucidate the underlying mechanism of increased expression of both IGF2 and IRS1 and aberrant activation of IGF-1R signaling in Herceptin-resistant breast cancer." (PMID 33976188, 2021). "However, the specific mechanism of IGF‐1 and IGF‐1R regulating breast cancer angiogenesis requires further investigation yet." (PMID 32548873, 2020). "IGF-1R belongs to the tyrosine kinase receptor family, and breast cancer cells that express IGF-1R may still be sensitive to lapatini b." (PMID 32223744, 2020). "The present study was aimed at evaluating the hypothesis that combined treatment composed of selective IGF1R inhibitor along with classical chemotherapy might be more effective than individual monotherapies in breast cancer treatment." (PMID 32391121, 2020). "Since the clinical finding of IGF‐1R pathway activation might be a factor for adjuvant tamoxifen failure, we performed functional studies in ER+ breast cancer cell lines to test this hypothesis in a controlled setting." (PMID 31490549, 2020). "In another study, a decrease in IGF1R expression has been associated with an improved chemotherapy response in patients with human EGFR2 negative breast cancer." (PMID 32577155, 2020). "Related to these findings, Yang and co-workers reported that the tyrphostin NT157 downregulates IRS1/2 proteins in breast cancer cell lines by binding to the IGF1R, increasing serine phosphorylation of IRS1/2, leading to their degradation and reduced IGF1R signaling." (PMID 32226608, 2020). "In this regard, a high IGF-1 gene expression signature mediating cancer proliferation and survival has been assessed in TNBC cells and primary TNBC specimens, hence suggesting a rationale for targeting the IGF-1/IGF-1R system in this highly aggressive breast cancer subtype." (PMID 32325700, 2020). "In addition, public databases of breast cancer patients were analyzed in order to address the impact of IGF1R expression on survival and to identify potential ‘signatures’ associated with improved survival." (PMID 32391121, 2020). "Finally, we show the potential usefulness of the dual IGF‐1R/InsR inhibitor linsitinib to overcome tamoxifen resistance in IGF‐1R‐driven ER+ breast cancer." (PMID 31490549, 2020). "Preclinical studies indicate that activated IGF‐1R can drive endocrine resistance in ER‐positive (ER+) breast cancer, but its clinical relevance is unknown." (PMID 31490549, 2020). "Here, we reveal that IGF‐1R pathway activation may be disadvantageous for the efficacy of adjuvant tamoxifen in postmenopausal ER+ breast cancer patients and that blocking this activated pathway may reverse this mechanism of endocrine therapy resistance." (PMID 31490549, 2020).
breast cancer (continued). "Additionally, we found that breast cancers from Black women had higher IR expression and were more likely to have an elevated IR/IGF-1R ratio than tumors from White women." (PMID 32393319, 2020). "Thus, IGF1R levels were differentially expressed with variable prognostic impact among breast cancer subtypes." (PMID 32391121, 2020). "Overall, our results confirm that positivity of p‐IGF‐1R/InsR might serve as a marker for better prognosis in ER+ primary breast cancer." (PMID 31490549, 2020). "Additionally, the overexpression of miR-152 inhibits breast cancer cell proliferation via targeting IGF1R and IRS1 and suppressing their downstream AKT and MAPK/ERK signaling pathways." (PMID 33291523, 2020). "The involvement of the INSR and IGF1R in breast cancer has been extensively reported." (PMID 32733384, 2020). "Given the vital roles of the INSR and IGF1R signaling pathways in breast cancer, and to gain new insight into potential commonalities and divergences in expression patterns between both receptors and their downstream mediators, we employed the BioNSi bioinformatics tool for network simulation." (PMID 32733384, 2020). "IGF-1R downregulation under LA treatment was also detected in other breast cancer cell lines." (PMID 31988347, 2020). "In breast cancer, the up-regulation of IGF1R and the activation of its downstream signaling molecules have been linked to an inhibition of apoptosis, disease progression, increased resistance to cytotoxic chemo-therapeutic drugs or radiotherapy, and to poor prognosis." (PMID 31269724, 2019). "IGF-1R and insulin receptor isoform A (IR-A) are frequently upregulated in breast cancer." (PMID 31455425, 2019). "Other investigators also found that hyperglycemia promoted the proliferation of malignant breast cancer epithelial cells by increasing leptin/insulin-like growth factor-1 receptor (IGF-1R) signaling and activating the Protein Kinase B/mechanistic target of rapamycin (AKT/mTOR) pathway." (PMID 31337431, 2019). "In addition, small interfering RNA technology was used to specifically down-regulate INSR or IGF1R expression in T47D breast cancer cells." (PMID 31771180, 2019). "However, increased expression of IGF-1R and/or IGF-1 is associated with various types of cancers, notably in breast cancer, in which breast cancer cells often coexpress IGF-1R and ERα." (PMID 30692633, 2019). "To explore this hypothesis, we evaluated the expression of IGF1R, which has previously been reported as a target gene of miR‐122 in breast cancer." (PMID 30938061, 2019). "However, the results of our study provide further evidence of the importance of the insulin and IGF-1R pathway in breast cancer." (PMID 31455425, 2019). "Interestingly, our recent data shows that HER3 and IGF-1R exhibit distinct effects upon the sensitivity of HER2-over-expressing breast cancer cells to lapatinib." (PMID 30930695, 2019). "Another phase II study of lower dose ridaforolimus with dalotuzumab, which inhibits autophosphorylation of IGF1R in ER+ advanced breast cancer had similar efficacy but with higher incidence of adverse events compared to treatment with the aromatase inhibitor, exemestane." (PMID 31817676, 2019). "Moreover, the analysis of IGF-1R expression in a cohort of breast cancer patients highlighted a strong correlation between IGF-1R and either ERα/Src or ERα/PI3K expression." (PMID 30692633, 2019). "Notably, our findings demonstrate that both JNK and Akt are commonly regulated by IGF-1R in SERM resistant breast cancer cells." (PMID 31815253, 2019). "It appears that IGF-1R expression and prognosis depends on the hormone status of the breast cancer." (PMID 30497427, 2018). "It would be worthwhile to investigate whether PI3K/IGF-1R signaling is affected in human breast cancers in future study, especially those showing increased cytoplasmic but reduced nuclear level of SIRT1." (PMID 30038266, 2018).
breast cancer (continued). "In our study, adjustment for ER status did not materially change the results and adjustment for breast cancer subtype led to slightly stronger associations of insulin with IGF1R and p-mTOR." (PMID 29486734, 2018). "Of 52 CTCs detected in patients with early breast cancer, 94% were IGF1R(+)/E‐cadherin(+)." (PMID 28766847, 2018). "(1997) reported similar immunohistochemical staining pattern for IGF1R in breast cancer tissues." (PMID 28766847, 2018). "Several studies have elucidated over-expression of IGF-1R in breast cancer progression." (PMID 29787591, 2018). "Peripheral blood mononuclear cells of early (n = 87)‐ and metastatic (n = 126)‐stage breast cancer patients (obtained prior to adjuvant and first‐line chemotherapy) were evaluated using double immunofluorescence (IF) staining for cytokeratin (CK) and IGF1R." (PMID 28766847, 2018). "(2013) reported that 84% of patients with breast cancer had IGF1R‐expressing CTCs." (PMID 28766847, 2018). "However, recent reports have suggested that overexpression of IGF-1R in ER+/PR+ breast cancers results in a favorable prognosis, and low expression of IGF-1R leads to a more undifferentiated tumor phenotype and worse overall survival." (PMID 30458886, 2018). "A cross talk between the ErbB/HER family and IGF1R signaling pathway has been proven in breast cancer and the evidences reported in this study supports the hypothesis that this mechanism could be also involved in this context." (PMID 29662006, 2018). "(2000) also showed that insulin receptor substrate‐1 (IRS‐1) and IGF1R are expressed at high levels in control tissues and in well and moderately differentiated carcinomas, but at significantly lower levels in poorly differentiated breast cancers." (PMID 28766847, 2018). "As a potential regulatory mechanism that promotes ER dependency for cell proliferation and survival in ER+ breast cancer cells, receptor tyrosine kinases (RTKs), such as EGFR and IGF1R, and their associated ligands, including IRS2, are putative targets of miR-7." (PMID 30214383, 2018). "Taken together, these data support the hypothesis that IGF-1R functions as a tumor suppressor in human breast cancer, and that reduced IGF-1R expression is detrimental to patient outcome." (PMID 30458886, 2018). "Moreover, cell culture supernatant from IGF-1Ea-transfected HEK293 cells treated with 2-DG fully activated the IGF-1R of MCF-7 breast cancer cells." (PMID 29891966, 2018). "Moreover, IGF-1R expression was lower in poorly differentiated, more aggressive basal-like breast cancers compared to the differentiated luminal A and luminal B subtypes as defined by PAM50 analysis." (PMID 30458886, 2018). "Based on our preclinical findings, we hypothesized that inhibition of ER decreases IGF-1R/InsR/PI3K/AKT signaling induced by mTORC1 inhibition in ER+ breast cancer." (PMID 29507656, 2018). "Moreover, IGF1R overexpressed in HER2+ breast cancer and forms a heteromeric complex with HER2 and HER3 to activate PI3K signaling pathway." (PMID 29455658, 2018). "Numerous studies have further confirmed cross-talk between the ER and IGF-1R in breast cancer." (PMID 30458886, 2018). "IGF1R colocalizes and coprecipitates with E‐cadherin in breast cancer cells." (PMID 28766847, 2018). "Therefore, upregulation of normal Ras activity by RTKs, such as the EGFR and insulin growth factor receptor (IGF1-R), has been shown in ERα positive breast cancer." (PMID 30208932, 2018). "In previous studies, we provided evidence that IGF1R may undergo nuclear translocation in breast cancer cells." (PMID 28706506, 2017). "However, satisfying treatment outcomes in breast cancer patients have yet to be achieved with IGF-1R-targeted agents." (PMID 28046018, 2017). "Thus, enhancement of ERBB2-mediated signal in EGFR1-directed antibody (cetuximab) and IGF1R-mediated signal in anti-erbB2/HER2 (trastuzumab) antibody-treated breast cancer patients confers resistance to the treatment." (PMID 29119846, 2017).